TOLLIP (toll interacting protein)
Description:
Component of the signaling pathway of IL-1 and Toll-like receptors. Inhibits cell activation by microbial products. Recruits IRAK1 to the IL-1 receptor complex. Inhibits IRAK1 phosphorylation and kinase activity. Connects the ubiquitin pathway to autophagy by functioning as a ubiquitin-ATG8 family adapter and thus mediating autophagic clearance of ubiquitin conjugates. The TOLLIP-dependent selective autophagy pathway plays an important role in clearance of cytotoxic polyQ proteins aggregates. In a complex with TOM1, recruits ubiquitin-conjugated proteins onto early endosomes. Binds to phosphatidylinositol 3-phosphate (PtdIns(3)P).
Synonyms: IL-1RAcPIP
Tractability: Antibody: its Gene Ontology location is reachable by antibodies, with high confidence. PROTAC: ubiquitination databases record sites on it; its protein half-life has been measured.
Gene: Protein-coding gene on chromosome 11 (1,274,371 to 1,310,258, reverse strand). Ensembl gene ENSG00000078902.
Subcellular location: Cytoplasm; Endosome; Early endosome
Subcellular location (Human Protein Atlas): Cytosol; Nucleoplasm; Primary cilium; Primary cilium tip
Pathways (Reactome):
Immune System: Interleukin-1 signaling; Neutrophil degranulation
Gene Ontology:
Molecular function: kinase binding; molecular adaptor activity; protein binding; Toll-like receptor binding; ubiquitin binding; ubiquitin conjugating enzyme binding; interleukin-1, type I receptor binding; SUMO binding; ubiquitin protein ligase binding
Biological process: epithelial cell differentiation; interleukin-1-mediated signaling pathway; phosphorylation; protein localization to endosome; signal transduction; leukocyte activation; ubiquitin-dependent protein catabolic process; positive regulation of protein sumoylation
Cellular component: cytoplasm; cytosol; early endosome; endosome; extracellular exosome; protein-containing complex; azurophil granule lumen; extracellular region; extrinsic component of plasma membrane; specific granule lumen; nuclear body; perinuclear region of cytoplasm
Genetic constraint (gnomAD): Loss-of-function variants: 14 observed, 29.31 expected, observed/expected ratio (o/e) 0.48, 90% interval 0.31 to 0.75. The upper end of that interval is the gene's LOEUF score, 0.75, which puts it in group 3 of 6, group 1 being the genes least tolerant of losing a copy. Missense variants: 305 observed, 375.2 expected, observed/expected ratio (o/e) 0.81, 90% interval 0.74 to 0.89. Synonymous variants: 166 observed, 157.64 expected, observed/expected ratio (o/e) 1.05, 90% interval 0.93 to 1.2.
Homologues: Orthologues: chimpanzee TOLLIP (97% identical), macaque TOLLIP (97% identical), rat Tollip (93% identical), mouse Tollip (93% identical), rabbit TOLLIP (93% identical), guinea pig TOLLIP (92% identical), dog TOLLIP (90% identical), pig TOLLIP (89% identical), zebrafish tollip (82% identical), tropical clawed frog tollip (80% identical), Caenorhabditis elegans tli-1 (38% identical).
Diseases named in the same sentence as TOLLIP in open-access papers:
TOLLIP is named in the same sentence as 88 diseases in open-access papers, as found by Europe PMC text mining. Sharing a sentence is not in itself a finding about the gene and the disease. The quoted sentences say what the papers report.
pulmonary fibrosis (15 papers, 2017 to 2026). Chronic progressive interstitial lung disorder characterized by the replacement of the lung tissue by connective tissue, leading to progressive dyspnea, respiratory failure, or right heart failure. "The TOLLIP rs3750920_T allele was significantly more frequent in idiopathic pulmonary fibrosis (IPF) than in controls (66.1% vs. 50.5%; p = 0.038)." (PMID 42058428, 2026). "Single nucleotide polymorphisms (SNPs) within Toll interacting protein (TOLLIP) coding gene have been associated with progression and prognosis of Idiopathic Pulmonary Fibrosis (IPF)." (PMID 40475958, 2025). "Different variants in TOLLIP reportedly have opposite effects on the risk of pulmonary fibrosis development." (PMID 39521375, 2025). "Genetic variants of TOLLIP have been demonstrated to be associated with various chronic lung diseases, including idiopathic pulmonary fibrosis, asthma, primary graft dysfunction following lung transplantation, and pulmonary infections." (PMID 39578840, 2024). "TOLLIP polymorphism has been implicated in the development and prognosis of idiopathic pulmonary fibrosis (IPF), mainly in whites." (PMID 34376770, 2021). "The biological mechanisms underlying the interaction of TOLLIP polymorphism with the pathogenesis of pulmonary fibrosis are not fully understood." (PMID 34376770, 2021). "Combined with the previous association of the same TOLLIP SNPs with IPF, our identification of TOLLIP SNPs associated with percent HAA suggests these SNPs play a role in subclinical disease progressing toward clinical development of pulmonary fibrosis." (PMID 28521775, 2017). "Finally, polymorphisms of mucins, i.e., MUC5B or Toll-like receptor inhibitors (TOLLIP), have been associated with a greater risk of developing pulmonary fibrosis." (PMID 36553114, 2022). "Also the results of the recent PRECISIONS trial are highly anticipated, which aims at addressing whether NAC has a differential effect on the progression of pulmonary fibrosis depending on the TOLLIP gene variant." (PMID 38730387, 2024). "Four SNPs were associated with pulmonary fibrosis in RA: beyond the well-known MUC5B polymorphism rs35705950 and the TERT polymorphisms rs2736100, TOLLIP (rs111521887) and FAM13A (rs2609255) were also associated with a higher risk of ILD." (PMID 40066169, 2025). "It has been reported that overproduction of mucin 5 B (MUC5B) or a decrease in TOLLIP exacerbates lung injury and pulmonary fibrosis." (PMID 40538533, 2025). "Mutations in telomere-related genes and surfactant proteins have been linked to familial pulmonary fibrosis, while variants in MUC5B and TOLLIP increase the risk of ILD, including idiopathic pulmonary fibrosis and rheumatoid arthritis-associated ILD." (PMID 39768847, 2024). "Genetic variants of TOLLIP and MUC5B, both on chromosome 11, have been reported to be associated with the development and/or prognosis of idiopathic pulmonary fibrosis (IPF)." (PMID 33639995, 2021). "Gene polymorphism involving inflammatory regulators may be associated with pulmonary fibrosis, which includes IL-1RN, IL-4, Toll-like receptor 3, and TOLLIP (Toll-interacting protein) among others." (PMID 40124525, 2025).
idiopathic pulmonary fibrosis (13 papers, 2017 to 2026). Idiopathic pulmonary fibrosis (IPF) is a nonneoplastic pulmonary disease that is characterized by the formation of scar tissue within the lungs in the absence of any known cause. "Genetic variants in human TOLLIP gene have been associated with idiopathic pulmonary fibrosis (IPF)." (PMID 28529512, 2017). "Sequence variants in genes for surfactant proteins (SFTPC, SFTPA1, SFTPA2, ABCA3), polymorphisms in MUC5B or TOLLIP, and mutations in telomere genes (TERT, TERC, PARN, and RTEL1) are associated with an increased risk of idiopathic pulmonary fibrosis (IPF)." (PMID 36864460, 2023).
tuberculosis (10 papers, 2013 to 2025). A chronic, recurrent infection caused by the bacterium Mycobacterium tuberculosis. "tuberculosis has been associated with polymorphisms in pathogen-sensing TLR pathway mediators such as Toll-interacting protein (TOLLIP) and TST1 and TST2 loci that influence TST reactivity." (PMID 31602294, 2019). "Several variants of the TOLLIP gene have been shown to be associated with tuberculosis and its transcription levels, cutaneous leishmaniasis and, leprosy." (PMID 28288644, 2017). "Two polymorphisms, rs5743899 and rs3750920, in the TOLLIP gene that is a negative regulator of TLRs signaling, are associated with tuberculosis in a Vietnamese population and with cutaneous leishmaniasis in the Amazonas state, Brazil." (PMID 28288644, 2017). "TOLLIP is a negative regulator of TLRs-signaling and two polymorphisms, rs5743899 and rs3750920, in the TOLLIP gene have been associated with tuberculosis in the Vietnamese population." (PMID 26107286, 2015). "In a case-population study in Vietnam, researchers found that SNPs rs5743899 and rs3750920 in the TOLLIP gene were associated with susceptibility to tuberculosis, which demonstrates that TOLLIP deficiency is associated with an increased risk of infectious disease." (PMID 34154540, 2021). "Interestingly, two variants (rs5743899 and rs3750920) of the TOLLIP gene associated with tuberculosis were shown to be associated with mRNA expression and TLR mediated cytokine release." (PMID 26107286, 2015).
Sepsis (6 papers, 2011 to 2015). Sepsis is defined as life-threatening organ dysfunction caused by a dysregulated host response to infection. "• Individuals carrying the T allele of rs5743867 and haplotype GCT in Toll-interacting protein (TOLLIP) gene have a higher risk of developing sepsis in the Chinese Han population." (PMID 21219635, 2011). "When patients with sepsis were compared with healthy controls, two tag SNPs in TOLLIP were observed in association with sepsis susceptibility." (PMID 21219635, 2011). "The minor allele C of rs5743867 in TOLLIP was associated with a decreased risk of sepsis (P = 0.00016, OR = 0.67, 95% CI 0.54 to 0.82), and the significance remained present after Bonferroni correction (P = 0.0026 corrected for 16 SNPs tested)." (PMID 21219635, 2011). "Our findings indicated that the variants in TOLLIP were significantly associated with sepsis susceptibility in the Chinese Han population." (PMID 21219635, 2011). "Five genes, namely TLR2, TLR4, TLR9, MyD88 and TOLLIP, were investigated for their association with sepsis susceptibility by a tag single nucleotide polymorphism (SNP) strategy." (PMID 21219635, 2011). "In our study, genetic and expression evidence indicated that a tag SNP in the intron region of TOLLIP was associated with sepsis susceptibility in the Chinese Han population by influencing the expression levels." (PMID 21219635, 2011). "To test this hypothesis, we conducted a case control study using a tag SNP approach to investigate the association of variants in TLR2, TLR4, TLR9, MyD88, and TOLLIP with susceptibility to sepsis in the Chinese Han population." (PMID 21219635, 2011). "Our results showed that the minor C-allele of rs5743867 in TOLLIP was significantly associated with the decreased risk of sepsis (Padj = 0.00062, odds ratio (OR)adj = 0.71, 95% confidence interval (CI) 0.59 to 0.86) after adjustment for covariates in multiple logistic regression analysis." (PMID 21219635, 2011). "SNP rs5743942 of TOLLIP also showed an association with sepsis susceptibility." (PMID 21219635, 2011). "Our results showed that a tag SNP rs5743867 in TOLLIP, which influences the expression of TOLLIP mRNA and the production of TNF-α and IL-6, was significantly associated with susceptibility to sepsis." (PMID 21219635, 2011). "Both allele and genotype distributions of the other 14 SNPs in TLR2, TLR4, TLR9, MyD88, and TOLLIP did not vary significantly between sepsis patients and healthy controls." (PMID 21219635, 2011).
viral infection (5 papers, 2017 to 2025). "TOLLIP (toll-interacting protein) is essential to immune cell activation, cell survival, pathogen defense, and other biological processes related to inflammation and innate immune response, which are crucial in virus infections like COVID-19." (PMID 40076669, 2025). "As for DDX58, NFκB1, TOLLIP, RIPK1, DDX3Y, TRIM25 and JAK2, which are involved in antiviral signalling transduction, both increased mRNA abundance and switched poly(A) sites eventually led to enhanced protein production following viral infection." (PMID 28233779, 2017).
atopic dermatitis (4 papers, 2007 to 2014). "Schimming and colleagues demonstrated that the -526G/C (rs5743854) polymorphism in the promoter region of TOLLIP is significantly associated with the susceptibility of atopic dermatitis, which is a common inflammatory skin disorder." (PMID 21219635, 2011). "However it has been observed that the same variation of TOLLIP gene showed borderline association with atopic dermatitis, which is a common chronic inflammatory skin disorder." (PMID 24294608, 2013). "We present first evidence for an association of TOLLIP variation with atopic dermatitis." (PMID 17362526, 2007).
breast carcinoma (4 papers, 2016 to 2022). "In breast cancer, the expression of TOLLIP was heterogeneous; in 25% of tumors, the expression was higher than in normal tissue, but in 35%, the expression was lower than in the control and increased during breast cancer progression." (PMID 36499030, 2022).
interstitial lung disease (4 papers, 2021 to 2026). A diverse group of lung diseases that affect the lung parenchyma. "This study represents the first meta-analysis investigating the relationship between TOLLIP genetic variants and clinical features of interstitial lung disease (ILD)." (PMID 39578840, 2024). "Aim of the present study was to investigate the association of TOLLIP SNPs with the presence, severity and outcome of interstitial lung disease (ILD) in patients with SSc." (PMID 40475958, 2025). "Genetic polymorphisms in Toll-interacting protein (TOLLIP) have been documented in relation to clinical manifestations of interstitial lung disease (ILD)." (PMID 39578840, 2024). "This study aimed to characterize single nucleotide polymorphisms (SNPs) in TOLLIP and MUC5B among patients with interstitial lung disease (ILD) and its subtypes." (PMID 42058428, 2026). "Many genome-wide association studies (GWAS) linked TOLLIP SNPs to different diseases, especially IPF and rheumatoid arthritis (RA) associated interstitial lung disease (ILD)." (PMID 40475958, 2025). "There were significantly fewer TOLLIP rs5743890 minor allele C carriers among individuals with interstitial lung disease (ILD) than among those without this condition (11.42% vs. 18.92%)." (PMID 39578840, 2024). "The present meta-analysis endeavors to elucidate the nexus between genetic variations in TOLLIP and the onset and prognosis of interstitial lung disease (ILD), with the overarching aim of providing insight into the pathophysiological underpinnings of ILD." (PMID 39578840, 2024).
colorectal cancer (3 papers, 2017 to 2024). A primary or metastatic malignant neoplasm that affects the colon or rectum. "In colorectal cancer models, TOLLIP deficiency resulted in neutrophil reprogramming, increasing tumor immune surveillance, T cell activation, and reducing tumor burden." (PMID 36499030, 2022). "SETDB1 methylates K473 of the lactate transmembrane transporter protein MCT1, which impedes MCT1-TOLLIP interaction and inhibits TOLLIP-mediated autophagic degradation of MCT1, leading to M2 polarization of TAMs in colorectal cancer." (PMID 39080807, 2024).
COVID-19 (3 papers, 2025). A disease caused by infection with severe acute respiratory syndrome coronavirus 2. "Common hubs in the RNA inflammation networks based on the four groups of COVID-19 severity included TOLLIP (toll-interacting protein) and TNFRSF4 (tumour necrosis factor receptor superfamily member 4)." (PMID 40362649, 2025). "This study aims to identify the association of FAM13A, DSP, TOLLIP, TERT, and THSD4 variants with severe COVID-19 and post-COVID-19 condition in a Mexican mestizo population." (PMID 40076669, 2025). "This suggests that TOLLIP, TNFRSF4, AGER, and GHRL are crucial inflammatory COVID-19 markers." (PMID 40362649, 2025). "These biological routes, including those involving the FAM13A, DSP, TOLLIP, TERT, and THSD4 genes, have not been entirely studied in COVID-19 and post-COVID-19 condition." (PMID 40076669, 2025).
hepatocellular carcinoma (3 papers, 2022 to 2025). A malignant tumor that arises from hepatocytes. "For example, TOLLIP stimulates the proliferation, migration, and metastasis of hepatocellular carcinoma (HCC) cells." (PMID 39735680, 2025). "In cancer, TOLLIP has been described to promote hepatocellular carcinoma via the PI3K/AKT pathway, and NPHP3 has been shown to regulate cancer cell viability by mediating the primary cilium formation." (PMID 37947626, 2023). "In hepatocellular carcinoma, TOLLIP overexpression increased proliferation, invasion, and epithelial–mesenchymal transition, accelerating tumorigenesis via the activation of the PI3K/AKT pathway." (PMID 36499030, 2022). "In hepatocellular carcinoma (HCC), TOLLIP expression was upregulated, associated with more rapid tumor growth in vivo, enhanced HCC cell migration, and proliferation in vitro." (PMID 36499030, 2022).
Huntington disease (3 papers, 2020 to 2022). Huntington disease (HD) is a rare neurodegenerative disorder of the central nervous system characterized by unwanted choreatic movements, behavioral and psychiatric disturbances and dementia. "TOLLIP was originally reported to mediate the clearance of Huntington’s disease-linked polyQ protein aggregates." (PMID 36550103, 2022). "TOLLIP overexpression seems to clear human cells of cytotoxic proteins containing glutamine repeats (polyQ) associated with Huntington’s disease by autophagy, while in TOLLIP-deficient cells the aggregation of polyQs was reported." (PMID 36499030, 2022). "PolyQ proteins in the Huntington’s disease mouse striatum can sequester TOLLIP away from STING, leading to reduced STING protein and dampened immune signaling." (PMID 36550103, 2022). "The removal of TOLLIP from STING upon treatment with polyQ proteins in vitro or endogenous polyQ proteins in Huntington’s disease (HD) mouse striatum dampens cGAS-STING signaling." (PMID 33643304, 2020).
leprosy (3 papers, 2013 to 2021). Leprosy is a chronic infectious disease affecting primarily the skin and peripheral nervous system. "Another SNP, rs3793964, in the TOLLIP gene was associated with an increased risk for leprosy and increased skin expression of TOLLIP and IL-1R antagonist." (PMID 34154540, 2021). "The objective of this study was to investigate the association of variants in the TOLLIP gene with susceptibility to leprosy in Mexican patients." (PMID 24294608, 2013). "Thus, beneficial or deleterious effects of TOLLIP in leprosy patients depend on expression level and time of exposure to proinflammatory cytokine." (PMID 24294608, 2013). "It is hypothesized that in leprosy patients high TOLLIP levels could generate a low inflammatory response against mycobacteria; however low TOLLIP levels could produce a sustained inflammatory response which is associated with tissue damage." (PMID 24294608, 2013). "TOLLIP, moreover, deregulated inhibition of this pathway might result in attenuated responses to the proinflammatory cytokines (IL-6 and TNF-α) suppression of TLR-mediated cellular responses and a role in the leprosy." (PMID 24294608, 2013).
lung disease (3 papers, 2024 to 2025). "In other fibrosing lung diseases, TOLLIP haplotypes have also been linked to disease susceptibility and survival." (PMID 40475958, 2025). "Given its role in inflammation regulation, autophagy, and vacuolar transport, TOLLIP is implicated in numerous pulmonary diseases, including IPF, COPD, asthma, and infectious diseases." (PMID 39768847, 2024). "This study also identified a subgroup of patients with the toll-interacting protein (TOLLIP) TT genotype in which NAC monotherapy was associated with a significant decrease in the composite endpoint of lung disease progression, hospital admission, transplantation, or death (hazard ratio 0.14)." (PMID 40226606, 2025). "Additionally, TOLLIP regulation may be altered by microRNAs, particularly the down-regulation of miR-31 (a tumor suppressor) in pulmonary diseases such as IPF." (PMID 39768847, 2024).